PDGFA (platelet derived growth factor subunit A)
Diseases named in the same sentence as PDGFA in open-access papers (continued):
Sharing a sentence is not in itself a finding about the gene and the disease.
tumor (continued). "The Platelet Derived Growth Factor Subunit A (PDGFa) is a major mitogen for connective tissue cells and other cell types, whose overexpression mediates autocrine stimulation of tumor cells, regulation of interstitial fluid pressure and angiogenesis." (PMID 33255335, 2020). "While not statistically, ACVR1 R206H, Cre, and PDGFA tumors lysates showed increased phosphorylated pSTAT3 levels as compared to RCAS Y, Cre, and PDGFA tumor lysates." (PMID 30833574, 2019). "It has been suggested that amplification of chromosome 7 together with loss of chr10 are very early genetic events GBM ontogeny, potentially because of the tumor driver PDGFA on chromosome 7." (PMID 29156675, 2017). "PDGFRA is more expressed in GBMs of the left temporal lobe than in those of the right one, whereas PDGFA expression is higher when the tumour is set on right frontal and parietal lobes as opposed to the left correspondents." (PMID 29127351, 2017). "Overall, the results were concordant; however, we observed loss or gain of PDGFA and PDGFRA in recurrent tumours of some patients." (PMID 19707201, 2009). "Immunohistochemical analysis showed that tumour cells express PDGFA in the cytoplasm, whereas PDGFRA was preferentially observed in the cytoplasmic compartment and rarely on membranes." (PMID 19707201, 2009). "PDGFA was expressed in 15 cases (60%) in the tumor cell component; 17 samples (68%) stained in the stroma, 14 of them were positive in both components, while 3 (12%) only in the stroma." (PMID 17014709, 2006). "This upregulation suggests a potential role for PDGFA in tumor progression and pathology." (PMID 39796775, 2025). "Interestingly, we found that ESM1 and PDGFB are expressed in the same tumor regions, while PDGFA and PDGFC seem to be mutually exclusive with PDGFB and ESM1." (PMID 39773984, 2025). "Together, these data revealed common features of GBM, including gain of chr.7 and loss of chr.10, lacking IDH1/2 mutations, high frequency of TERT promoter mutation, loss of critical tumor suppressors (e.g., PTEN and CDKN2A/CDKN2B), high frequency of PDGFA and EGFR amplification." (PMID 34987659, 2022). "For example, tumor epithelial cells expressing PDGFA interacted with PDGFRA-expressing fibroblasts." (PMID 34976204, 2022). "Moreover, a recent study revealed that PDGFA/PDGFRα-regulated GOLM1 critically enhances the tumor progression ability through activating AKT signaling in GBM." (PMID 35874629, 2022). "In addition, our study showed a positive correlation between PDGFA expression and tumor-infiltrating macrophages." (PMID 36588538, 2022). "We found that B16F10 cells express substantially higher mRNA levels of the TIE2 ligand Angiopoietin‐2 (Ang2) compared to LLC1 and 4T1 tumor cells, whereas Ang1, Platelet‐Derived Growth Factor Alpha (PDGFA), and Fibroblast Growth Factor2 (FGF2) are similarly expressed (Fig EV1C)." (PMID 34102002, 2021). "In addition to increase of stemness, we also demonstrated the promotion of tumor angiogenesis by KDM2A via PDGFA and JAG1." (PMID 27029061, 2016). "Our study indicated that Nrf2 expression in HCC could not only increase PDGFA generation but also upregulate PDGFRα expression, leading to autocrine signaling in tumor cells." (PMID 27588483, 2016). "Additionally, the downregulated fibroblast growth factor receptors 3 and 4, PDGFA, and GAB1 (GRB2-associated binding protein 1), which take part in FGF signaling, indicate downregulation of this pathway and possible suppression of tumor cell invasiveness and EMT." (PMID 37834191, 2023). "A cascade of pro-tumorigenic factors, including IL6, VEGFA, IL11, PDGFA, and CXCL12, further amplify the formation of complex microenvironments that support tumor cell colonization and proliferation, exacerbating the progression of CRLM." (PMID 39979806, 2025).
tumor (continued). "Tumor-derived VEGFA and TGFβ2 signals were received by NRP2 and TGFβR2/3 receptors present on MES and RG-PC cells, respectively, with PDGFA_PDGFRA signaling from tumor cells directing final PC specification." (PMID 40562749, 2025). "In therapy‐induced tumour senescence, there is an enhanced expression of pro‐angiogenic factors (FGF2, VEGF and PDGFA/B) and MMPs (MMP2/3/7/9/10)." (PMID 39270064, 2024). "We also observed that tumor and endothelial cells released vascular endothelial growth factors, including VEGFC and VEGFA, as well as platelet-derived growth factors, including PDGFA and PDGFC." (PMID 37333982, 2023). "In concert, tumor cells and CAFs secrete pro-angiogenic factors such as VEGF, FGF2, PDGFA and PDGFB." (PMID 37091337, 2023). "Pericytes play a crucial role in tumor neovascularization; consistently, we observed a strong angiogenic signature (such as for ANGPT2, CAV1, PDGFA, THY1, EGFL6, and GMFG) in pericytes." (PMID 37853464, 2023). "Principal component analysis stratified the tumor types and as expected, IDH1-mutant tumors expressed increased levels of OLIG1 while IDH-wt GBM tumors expressed PDGFA among other stratifying genes." (PMID 38077210, 2023). "Among these DETs, multiple genes, including STAT3, PDGFA, PLD2, and PIK3R2, have been reported to be involved in tumor growth." (PMID 35291563, 2022). "The results indicated that the expression of tumor cell-derived VEGFA, IGFBP3, EFNA1, EFNB1, IGF2, PDGFA and stroma-derived Angpt2, Cdh5, Esam, Esm1, Icam2, and Tie1 was statistically correlated with that of Pecam1 and elevated in p-EMT TW2.6 tumors." (PMID 34869001, 2021). "Currently TNF, WNT10A, PDGFA, and NRG1 secreted by infiltrated dendritic cells in the tumor microenvironment were identified to be likely involved in the neuropathic pain using RNA-seq, scRNA-seq, and ChIP-seq data." (PMID 32434423, 2020). "The paracrine factors such as TNF, WNT10A, PDGFA, and NRG1 were also elevated in tumor-infiltrating dendritic cells." (PMID 32434423, 2020). "Among these CEBPD-responsive genes, PDGFA (platelet-derived growth factor subunit A), downregulated in CEBPD-knockdown U373MG cells, was of great interest in our study because of its critical role in tumor progression." (PMID 31300060, 2019). "We also identified transcriptional upregulation of PDGFA and CXCL8/IL8 and corresponding increased secretion of PDGF-AA and IL-8, two factors that can influence tumor inflammatory cell content and vascular proliferation." (PMID 29643433, 2018). "Tumour angiogenesis is mainly driven by vascular endothelial growth factor alpha (VEGFA) and platelet-derived growth factor alpha (PDGFA) in response to certain stimuli derived from the tumour cells directly or from the surrounding microenvironment." (PMID 25734337, 2015). "In IGF2-low tumors, other growth factors (FGF9, PDGFA) are more expressed than in IGF2-high tumors, suggesting that they play a compensatory role in tumor progression." (PMID 25089899, 2014). "Further, this study also identifies the potential of the extracted polyphenols on major tumor progression molecular targets including NFκB, EGFR, kRAS, STAT3, VEGF, AKT, TERT, FGFA, BCl2 and PDGFA." (PMID 23613993, 2013). "PDGFA/PDGFR-α functions via autocrine and paracrine signals to stimulate interstitial hyperplasia and indirectly promote tumor growth; in addition, it can promote cell proliferation by strengthening the response of IGF-1." (PMID 22217202, 2012). "In 22 cases, it was possible to analyse PDGFA and PDGFRA expression in both primary and recurrent tumours." (PMID 19707201, 2009). "The most frequent (occurring in six tumours) and prominent (up to 3-4-fold) increases were detected in the dosages of KRAS2 (on chromosome 12p) and PDGFA (chromosome 7p), relative to a reference locus from chromosome 2." (PMID 1829952, 1991).
tumor (continued). "Additional ARGs, including PDGFA, VTN, and POSTN, revealed intricate and subtype-specific correlations with both macrophages and T cells, reinforcing their involvement in shaping the tumor immune landscape." (PMID 40943183, 2025). "Our results indicated that HSV-PDGFi-shRNA could significantly downregulate the PDGFB level in the xenografts, but PDGFA level, and PDGFBB knockdown effectively inhibited tumor growth." (PMID 38378786, 2024). "CNV-gained ARGs, including PDGFA, were profoundly downregulated in tumor tissues, whereas CNV-amplified and deletion ARGs were not significantly differentially expressed." (PMID 36909170, 2023). "Concerning HCC, it has been confirmed that the platelet-derived growth factors (PDGF, including PDGFA, PDGFB, PDGFC, and PDGFD) participate in modulating the tumor development and chemoresistance by interacting with its receptor PDGFR and activating the downstream signaling pathway." (PMID 36463115, 2022). "Amplification of PDGFA gene and EGFR gene was detected in 7 tumor foci." (PMID 34987659, 2022). "High frequency of genetic alterations of tumor suppressors (e.g., PTEN and CDKN2A/CDKN2B) and oncogenes (e.g., PDGFA and EGFR) suggested that these cancer driver genes might be responsible for initiation of mGBM but not contribute to the progression of mGBM." (PMID 34987659, 2022). "We found that bufalin could inhibit the tube formation, adhesion and migration of HUVECs mediated by CAFs, TAMs and tumour cells by inhibiting the activation of HUVEC STAT3 and thereby decreasing the expression of VEGF, PDGFA, E-selectin, and P-selectin." (PMID 34496870, 2021). "Additionally, the box-and-whiskers plots indicated that WNT10A, PDGFA, and TNF were out of normal distribution due to extremely high expression in many tumor patients which were individually labeled with dots." (PMID 32434423, 2020). "However, in combination with PDGFA signaling, ACVR1 R206H and H3.1K27M significantly decrease survival and increase tumor incidence." (PMID 30833574, 2019). "In addition, fibroblast proliferation and mesenchymal cell proliferation were significantly enriched GO terms; the expression levels of TGFβ1, S100A6, PDGFA, and BMP7 were enriched in organoids (and tumor), compared with fetal retina." (PMID 30353124, 2018). "Differently, PDGFC is less expressed in microvascular proliferation in comparison to all other GBM regions aside from hyperplastic blood vessel and leading edge, and similarly to PDGFA and PDGFRA, it bears a preferential expression in cellular tumour bulk over leading edge." (PMID 29127351, 2017). "In addition, we found that the Classical markers FGFR3, PDGFA, EGFR, AKT-2 and Nestin are highly expressed in intracranial tumor tissue derived from bulk tumor cells and Sp-GSCs, while there is lower expression in Ad-GSC intracranial tumors." (PMID 25955030, 2015). "Also, to dissect out the benefit of anti-oxidant rich seaweed polyphenols in targeting tumor progression markers, first, we investigated the transcriptional regulation of Bcl2, EGFR, PDGFA, VEGF, AKT, TERT, kRas and FGF in PC cells." (PMID 23613993, 2013). "Six genes, RPL13A, KLF6, LOC100129599, GBE1, PDGFA, and UHRF1 were altered in lymph node metastases of both cell lines relative the primary tumor, suggesting they may represent changes important for metastatic growth in lymph nodes." (PMID 23118918, 2012). "Since the involvement of EPHA2 in PDGFA signaling, we examined whether EPHA2 had roles in tumor growth and invasion of GBM cells through MTT assay an Matrigel-coated transwell assay in the context of PDGF-AA stimulation, which indicated that EPHA2 knockdown decreased viability and invasiveness." (PMID 35105853, 2022). "The current research identified that infiltrated dendritic cells in the tumor microenvironment could synthesize hormones and secret the paracrine factors such as TNF, WNT10A, PDGFA, and NRG1 which could sensitize sensory neurons to promote neuropathic pain associated with multiple cancers." (PMID 32434423, 2020).
tumor (continued). "Furthermore, H3.3K27M can substitute for H3.1K27M mutation and cooperate with ACVR1 R206H in tumor initiation as mice that were infected with ACVR1 R206H, H3.3K27M, Cre, and PDGFA also had a high tumor incidence (20/22 = 91%) similar to ACVR1 R206H, H3.1K27M, Cre, and PDGFA." (PMID 30833574, 2019). "We also found that PDGFA overexpression was regulated by the EGF–STAT3 pathway, implying that the PDGF-AA binding receptor PDGFRαα served as another potential driver activating Wnt signaling, which could be a potential target against tumor recurrence." (PMID 30068339, 2018). "Instead, extracellular components, including LIF, CCL2, PDGFA, Hippo/YAP1, as well as, immune responses and angiogenesis, might pivotally participate in development of intratumor heterogeneity through remodeling methylome and transcriptome of tumor foci from same mGBM patients." (PMID 34987659, 2022). "Finally, PDGFA and CSF-1 were highly expressed in this cluster suggesting tissue-remodeling properties essential for wound healing, which combined with upregulated TXN93 improve their capacity to create an immunotolerant environment and promote tumor progression." (PMID 33602930, 2021). "Importantly, western blot analyses showed that along with these augmented levels of lytic gene expression, PDGFA and PDGFB correlated with prominent PDGFRA phosphorylation in tumor samples, suggesting that it could be a result of lytic induction occurring during in vivo tumorigenesis." (PMID 29985958, 2018). "Genes involved in tumour progression including non-integrin membrane-ECM interactions, COL4A and PDGFA, showed a gain of H3K4me3 in our dataset, in keeping with epigenetic regulation of these mechanisms being critical." (PMID 39915814, 2025). "In RNA dot blot assays the expression of KRAS2, PDGFA, EGFR, or MYC was generally not increased in the tumour samples when compared to that in normal testicular tissue of the same patients although there was interindividual variation in mRNA levels." (PMID 1829952, 1991). "In the IHC study, tumor cells showed positivity for CD99, EMA, vimentin, and TLE1, while they were negative for NKX2.2, WT1, BCOR, PDGFA, cytokeratins, muscle markers (smooth muscle actin, desmin, caldesmon, MyoD1, and myogenin), and melanocytic markers (HMB45, SOX10, and S100)." (PMID 38339014, 2024). "OS cells (Saos–2 cell line) downregulate the expression of angiogenic factors, such as CD34, PDGFA, PDGFRA, PDGFRB, and VEGF, in human AD-MSCs when co-cultured, implying that MSCs cannot differentiate in vitro under the induction of tumor cells and do not support tumor angiogenesis in vivo." (PMID 34681692, 2021).
cancer (73 papers, 2005 to 2025). A tumor composed of atypical neoplastic, often pleomorphic cells that invade other tissues. "PDGFA is a protein that has been implicated in cancer initiation and progression." (PMID 39869563, 2025). "Both VCAM1 and PDGFA are associated with angiogenesis and involved in cancer development." (PMID 35565312, 2022). "In metastatic vs. primary cancer comparison (Datasheet S9), we found platelet-derived growth factor subunit A (PDGFA) upregulated (0.67)." (PMID 41226816, 2025). "High levels of PDGFA have been reported in various cancers, where it promotes cancer cell invasion and proliferation." (PMID 39012409, 2024). "Cancer associated fibroblasts (CAFs) of ATLL play an important role for CD4 T-cell proliferation via FGF7-FGF1 and PDGFA-PDGFRA/B signaling, and CAFs, particularly EGR-enriched, are also associated with CD8 and NKT expansion by EGFR." (PMID 35464471, 2022). "Although it has been reported that PDGFA probably contributes to the carcinogenesis and progression of tumors, PDGFA exerts different roles in various types of cancers." (PMID 34011067, 2021). "The results revealed that PDGFA mRNA level was statistically increased in cancer tissues compared to normal tissues (P < .05)." (PMID 34011067, 2021). "Previous studies have demonstrated that PDGFA contributes to cancer stemness, but the molecular mechanisms driving PDGFA expression in GSCs under IL-1β treatment are still not elucidated." (PMID 31300060, 2019). "PDGFA targeting with the PDGF receptor has been reported to increase chemotherapeutic sensitivity in different cancers." (PMID 29342159, 2018). "Six genes, including ADD3, CTNND1, EPB41L3, F3, MUC4 and PDGFA, showed cancer-tissue-specific DES events." (PMID 22905095, 2012). "High PDGFA levels correlate with poor survival rates in high-grade carcinomas." (PMID 41155410, 2025). "Similar phenomenon was observed in the interaction between PVL and cells with hc10 state by PDGFA-PDGFRB complexes, implying the importance of PVL in shaping this CCS with cancer progression-associated biological functions, such as angiogenesis, EMT and extracellular matrix organization." (PMID 38472225, 2024). "Moreover, the PI3K-AKT pathway has been validated as the downstream signaling pathways of ALKAL2-ALK signaling and PDGFA-PDGFRB signaling in human cancers." (PMID 38812530, 2024). "However, this study also shows unexpected up-regulation of crucial genes and kinases (e.g., ERBB4, PLCβ4, PRKAR2B, and PDGFA) whose roles in cancer development and progression are crucial." (PMID 36430510, 2022). "In NetworkAnalyst analysis, KEGG associated with cancer pathways showed that PDGFA was indicative and STAT3 may be involved in activating the formation of cancer stem-like tumorspheres." (PMID 30068339, 2018). "Thus, STAT3 is capable of exacerbating β-catenin and inducing PDGFA to promote Wnt signaling for maintaining the formation and survival of cancer stem-like tumorspheres in selective EGFR-positive CRCs." (PMID 30068339, 2018). "In addition, PDGFA was one of the top ten down-regulated genes and also involved in the pathways in cancer." (PMID 29439675, 2018). "Cytokines such as TNF, growth factors including PDGFA and NRG1, and others like WNT10A were identified to interact with their receptors on neurons or other cells such as microglial cells to directly or indirectly sensitize neuropathic pain associated with cancers." (PMID 32434423, 2020). "Of these genes, CTHRC1, PDGFA, and IL7 were also shortlisted as matrisome genes of interest in the pan-cancer analysis." (PMID 36190948, 2022). "This identified 3 matrisome genes, CTHRC1, PDGFA and IL7 to be prominent candidates of which only CTHRC1 was upregulated in pan-cancer and 3 individual cancers making it the matrisome gene of interest." (PMID 36190948, 2022).